INS (insulin)
Diseases named in the same sentence as INS in open-access papers (continued):
Sharing a sentence is not in itself a finding about the gene and the disease.
Insulin resistance (continued). "Given the important role insulin signaling plays in driving signaling pathways that promote aggressive cancer biology, more attention should be paid by cancer physicians to screening and treating insulin resistance." (PMID 32153503, 2020). "Therefore, in the present study, we aimed to elucidate the effects of CYC31 on the insulin signaling pathway, fatty acid-induced insulin resistance, and fatty acid oxidation signaling in C2C12 myotubes." (PMID 32438641, 2020). "In NA/STZ-injected rats, it was explained that insulin resistance, serum insulin level, and glucose intolerance may be attributed to a significant degree by changes in the serum FFA level." (PMID 32655759, 2020). "It is reported that obesity and overweight can lead to a high level of serum leptin, which may because that obesity always accompanies with insulin resistance and hyperinsulinemia, and insulin further enhance the expression of leptin." (PMID 32819324, 2020). "In addition, it induced glucose intolerance, insulin resistance and compensatory increase of insulin secretion by pancreatic β-cells." (PMID 32187264, 2020). "This suggests that Pt-PS can alleviate insulin resistance and enhance insulin sensitivity." (PMID 32971772, 2020). "In turn, this might lead to a decrease in β-cells’ mass which results in its dysfunction with low insulin gene expression, resulting in lower insulin secretion and insulin resistance, increasing the impairment of T2DM condition." (PMID 32927739, 2020). "Insulin resistance has also been suggested to lead to decreased levels of insulin crossing the BBB." (PMID 33100956, 2020). "Interestingly, insulin infusion for several hours is able to suppress the expression of TLRs on monocytes from people with T2D, suggesting that insulin resistance promotes higher expression of TLRs (and thereby inflammation)." (PMID 33178196, 2020). "Curcumin treatment reduced both serum insulin and insulin resistance (measured via HOMA2-IR)." (PMID 32283762, 2020). "Notably, lipid accumulation in muscle occurred (1wk) before the elevation of plasma insulin and onset of insulin resistance, implying the importance of lipid species in the induction of insulin resistance." (PMID 31938068, 2020). "Chronic exposure to proinflammatory mediators stimulates the activation of cytokine signaling proteins which ultimately block the interaction between the activation of insulin signaling pathway, biological function of pancreatic β-cells, and conduce to insulin resistance." (PMID 33293987, 2020). "In addition, the hyperinsulinemia impairment of insulin signaling and insulin resistance are the vital factors that make the sense of keeping insulin at the center stage of both pathologies irrespective of genotype." (PMID 32365816, 2020). "Individuals with Alzheimer’s Disease (AD) are often characterized by systemic markers of insulin resistance; however, the broader effects of AD on other relevant metabolic hormones, such as incretins that affect insulin secretion and food intake, remains less clear." (PMID 33328877, 2020). "HOMA-IR and HOMA-β could reflect the levels of insulin resistance and insulin secretion during the course." (PMID 32184821, 2020). "Furthermore, central nervous insulin resistance in overweight people leads to blunted postprandial satiety signals and brain-derived regulation of peripheral insulin sensitivity is impaired in obese patients." (PMID 33047031, 2020). "In addition, we observed significant improvements in measures of insulin resistance and insulin sensitivity as measured by HOMA-IR and HOMA-%S at both 1 and 6 months postoperatively." (PMID 32067166, 2020). "The male progeny only showed modifications in lipid metabolism in adulthood, whereas in female offspring, we observed an increase in the insulin level, indicative of insulin resistance, and a lipid metabolism alteration at both ages, indicating a sex-dependent metabolic disruption." (PMID 32023917, 2020).
Insulin resistance (continued). "Thereby, dysfunctional insulin production occurs, gradually leading to insulin resistance." (PMID 32982969, 2020). "Particularly, in patients with type-2 diabetes, insulin resistance is well-demonstrated and they might often need to take oral antidiabetic drug or insulin administration, to control the development of the pathology, as well as the DN." (PMID 32466228, 2020). "Type II diabetes mellitus causes chronic oxidative stress as a consequence of hyperglycemia, insulin resistance, inflammation and dyslipidemia, and may result in defective expression of insulin gene and impaired insulin secretion." (PMID 33322700, 2020). "In consequence, insulin production increases and the improvement of insulin resistance is observed." (PMID 33298009, 2020). "Insulin resistance arises from defective insulin action in its target tissues—primarily skeletal muscle, liver and white adipose tissue—either as a result of insulin receptor defects or much more commonly due to perturbations in the post-receptor insulin signaling cascade." (PMID 32574288, 2020). "In addition, insulin resistance in T2DM has been defined as “reduced sensitivity in body tissues to the action of insulin”." (PMID 32365816, 2020). "This suggests that high AhRL and/or low MIS-ATP may be involved in the impairment of insulin secretion and insulin resistance." (PMID 32286339, 2020). "Pro-inflammatory adipokines (IL-6, TNF-α, MCP-1) and leptin, associated with the maintenance of the obese state, are elevated during the obese state whereas adiponectin, which plays an important role in insulin sensitivity, is decreased, connecting its role to insulin resistance and T2DM." (PMID 32903449, 2020). "Indeed, in a study on 959 participants, handgrip strength was inversely related to insulin resistance (p = 0.025) and fasting insulin levels (p = 0.017)." (PMID 32183393, 2020). "Potentially, an even longer insulin treatment could level such discrepancies and lead to the same outputs in the two cell models, as well as give a closer representation of insulin resistance in vivo." (PMID 32718202, 2020). "However, Napepld∆Hep mice exhibited a higher insulin resistance index, mainly explained by elevated plasma insulin levels." (PMID 32443626, 2020). "Regarding the association between MR-proADM and insulin resistance, we found that higher MR-proADM levels were positively rather than inversely associated with fasting insulin, HOMA-IR and HOMA-B at follow-up." (PMID 33066780, 2020). "17-OH progesterone levels correlated negatively with weight, BMI, waist circumference, insulin, homeostatic model assessment of insulin resistance (HOMA-IR), and visceral fat, and positively with TT, free testosterone (FT), luteinizing hormone, and fat-free mass percentage." (PMID 33260786, 2020). "Moreover, administration of DCI or MI restores normal insulin sensitivity in some situations of insulin resistance." (PMID 32650579, 2020). "This bewildering result suggested that TCC exercise might consume more glucose and insulin and induce more increase in insulin resistance, and consume less TC and HDL-C and induce less increase in insulin sensitivity in the TCC practitioners 30 min after TCC." (PMID 32784834, 2020). "Furthermore, the concomitant decrease in serum insulin level and improvement of glucose tolerance suggested that ALO is helpful to enhance insulin sensitivity and relieve insulin resistance." (PMID 33568989, 2020). "Reduced insulin clearance should be considered with regard to vascular insulin resistance." (PMID 33384433, 2020). "The differences in insulin resistance may also be related to differences in insulin metabolism between races." (PMID 32393319, 2020). "In addition, SHR-Glo1+/− heterozygotes compared to SHR exhibited ameliorated insulin resistance when they had lower serum insulin levels and their adipose tissue was more sensitive to insulin action, as indicated by increased insulin-stimulated lipogenesis." (PMID 33255888, 2020).
Insulin resistance (continued). "T2D has two main components, insulin resistance and a progressive failure in insulin secretion." (PMID 32927754, 2020). "ASX treatment was also reported to ameliorate insulin resistance and improve insulin signaling by activating post-receptor insulin signaling, to reduce the oxidative stress produced by various stimuli including TNF-α, and to inhibit pro-inflammatory cytokines in obese mice." (PMID 32260306, 2020). "Additionally, febuxostat significantly decreased plasma insulin concentrations in CL-fed mice under fasting conditions, resulting in lower homeostasis model assessment of insulin resistance (HOMA-IR), a marker for insulin resistance." (PMID 31965018, 2020). "Also, CA treatment of both high-fat diet-induced obese mice and spontaneously obese mice reduced hyperinsulinemia and enhanced insulin sensitivity, suggesting that CA can improve obesity-related insulin resistance." (PMID 32566690, 2020). "Besides, hyperglycemia was reversed by chronic dosing of HSP90 inhibitors in the diabetic db/db mouse model, and insulin sensitivity was made better in the diet-induced obese mouse model of insulin resistance." (PMID 33841528, 2020). "Our study, together with previous evidence, suggests that insulin and insulin resistance have symbiotic roles that may both ultimately play a role in CVD." (PMID 31508506, 2019). "Thus, in insulin resistance states, higher levels of plasma glucose are observed with higher insulin levels required to compensate for the hyperglycemia." (PMID 31608010, 2019). "Also, patients having a rare homozygous mutation of DBH gene, showed impaired cardiovascular autonomic regulation, enhanced glucose-stimulated insulin secretion, and insulin resistance, the co-morbidities also observed in women with PCOS." (PMID 30946770, 2019). "Metabolic traits including fasting insulin (rG = 0.17, p = 0.53), homeostatic model assessment of insulin resistance (rG = 0.37, p = 0.48), fasting glucose (rG = 0.01, p = 0.97) and coronary artery disease (rG = −0.01, p = 0.97) were not genetically correlated with liver iron content." (PMID 31226389, 2019). "Indeed, olanzapine-induced increases in blood glucose are ablated in glucagon receptor knockout mice, despite the onset of olanzapine-induced insulin resistance (as measured by an insulin tolerance test)." (PMID 31555747, 2019). "Taken together, these lines of evidence present the possibility that changes in SUMOylation levels in T2DM could aberrantly affect insulin signalling and therefore contribute to skeletal muscle insulin resistance." (PMID 31019221, 2019). "Insulin resistance is a pathological condition in which insulin-sensitive tissues including the liver and adipose tissue fail to respond to normal circulating levels of insulin." (PMID 31075962, 2019). "However, the dose at 100 mg/kg b.wt showed a significant reduction in the levels of plasma glucose and Homeostatic Model Assessment of Insulin Resistance with concomitant elevation of insulin when compared to the other two doses (25 and 50 mg/kg b.wt)." (PMID 32219004, 2019). "Studies have suggested that DUSP9 promotes obesity-related insulin resistance; in adipocytes, DUSP9 may promote insulin resistance by inhibiting insulin-stimulated differentiation and glucose uptake." (PMID 31772940, 2019). "However, the impact of CPAP therapy on DM is less clear in research measuring the variable markers of insulin sensitivity and insulin resistance." (PMID 31557884, 2019). "Insulin resistance is inversely correlated with insulin sensitivity in insulin-dependent tissues." (PMID 31035653, 2019). "After the Silverrobics exercise program, there were significant decreases in the glucose (p<0.05), glycated hemoglobin A1c (p<0.05), 1,5-anhydroglucitol (p<0.05), and insulin levels (p<0.01) and homeostatic model assessment of insulin resistance score (p<0.05)." (PMID 31010271, 2019).
Insulin resistance (continued). "Therefore, hypothalamic insulin resistance is partly explained by disrupted insulin transport into the brain." (PMID 30875909, 2019). "A recent meta-analysis of prospective interventional studies have shown that PEGV, in monotherapy or combined with SRLs, improves glucose metabolism by reducing fasting plasma glucose and insulin levels, HbA1c, and insulin resistance, independently of disease control." (PMID 31365632, 2019). "On the other hand, another unexplored possibility is that insulin resistance might be the driver responsible for the changes in lymphocyte populations, which would reverse after bariatric surgery-related improvement in insulin sensitivity." (PMID 31885787, 2019). "Also homeostatic model assessment insulin resistance, insulin, and high-density lipoprotein cholesterol parameters were significantly higher in pregnant women in the NES group (p<0.05)." (PMID 31360584, 2019). "Again, the positive linear correlations found between CCK and IL-1, IL-1, and GIP, and GIP and insulin (other anorexigen) may perpetuate the anorexia and the insulin resistance suffered by our patients." (PMID 31191339, 2019). "In the present study, we showed that IOE treatment has similar effects to metformin to ameliorate insulin resistance, glucose intolerance, and dyslipidemia in mice, probably through activation of the insulin signaling pathway and upregulation of GLUT4 expression." (PMID 31323977, 2019). "Decreasing insulin resistance through insulin-sensitizing drugs (e.g., metformin, rosiglitazone, pioglitazone, and d-chiro-inositol) and/or lifestyle treatments could improve the reproductive and metabolic outcomes for patients with PCOS." (PMID 31507635, 2019). "The worsening of the insulin resistance observed on the intervention group associated with steatosis by CAP could be transitory and followed by recovery of insulin sensitivity after therapy suspension, as has already been established." (PMID 31275240, 2019). "The majority of known type 2 diabetes-related genetic risk variants are associated with insulin secretion rather than insulin resistance." (PMID 30971952, 2019). "These beneficial impacts of BCAA catabolic defect on insulin sensitivity are opposite to its stimulatory effects on insulin resistance in obese mice, supporting the notion that BCAAs exert different metabolic effects depending on the catabolic and anabolic states." (PMID 31551816, 2019). "Moreover, endothelial dysfunction and impaired nitric oxide-mediated vasodilatation have also been suggested to directly lead to reduced insulin delivery to skeletal muscles, resulting in peripheral insulin resistance and hyper-glycaemia." (PMID 31330868, 2019). "The generation of ROS may also interfere in insulin signalling in muscle, contributing to insulin resistance in type 2 diabetes; moreover, the mitochondrial function has been shown to affect insulin sensitivity in the muscle, liver, and adipose tissue." (PMID 31781665, 2019). "The serum BCAAs level of T2DM rats were increased, and HS treatment could significantly reduce the level of BCAAs, indicating that HS could treat T2DM by reducing insulin resistance, improving insulin sensitivity, and regulating protein metabolism." (PMID 31717456, 2019). "Systemic insulin resistance and decreased insulin-induced phosphorylation of AKT in the liver." (PMID 31139087, 2019). "In addition, under normal conditions, skeletal muscle mediates the majority of insulin-stimulated whole-body glucose disposal, and inflammation of muscle with its dysregulation leading to increased insulin resistance is seen in obesity." (PMID 31608014, 2019). "The disturbances in insulin pathway are responsible for the development of insulin resistance." (PMID 30959886, 2019). "Thus, SOCS3 was a good candidate to negatively regulate insulin signaling at early time-points, prior to the delayed (7 days) insulin resistance that we found." (PMID 31160730, 2019).
Insulin resistance (continued). "If this observation holds true in T2DM patients, TRPV1 antagonists may be promising drug candidates to treat impaired glucose tolerance, insulin secretion, and insulin resistance." (PMID 31344877, 2019). "Recent evidence also shows that celastrol, a tripterine isolated from the root extracts of Tripterygium wilfordii plant, could ameliorate hepatic insulin resistance by improving insulin signaling and mitochondrial function." (PMID 31048842, 2019). "Daily consumption of probiotic yoghurt for 9 weeks was effective in maintaining normal serum insulin levels in pregnant women and thus contributing to prevent the development of insulin resistance, which usually develops during the last trimester in pregnant women." (PMID 31485272, 2019). "Next, we assessed whether accumulation of 2-AAA leads to insulin resistance, which could occur through impaired insulin signaling and abnormal gluconeogenesis." (PMID 31541119, 2019). "Observations obtained in assessing our LTCFDN mouse model also prompted us to speculate whether β-cat/TCF is a “missing link” for understanding the paradox of hepatic insulin function and insulin resistance." (PMID 31589598, 2019). "IRS-1 is a key molecule in insulin signaling and its down-regulation leads to insulin resistance." (PMID 31723029, 2019). "Comparison with NGT may make the involvement of insulin secretion failure and insulin resistance in GDM clearer." (PMID 31275653, 2019). "Indeed, peripheral hyperinsulinemia and insulin resistance can decrease insulin receptors expression at the blood-brain barrier, and reduce the insulin transport into the brain." (PMID 31440156, 2019). "Impairing insulin signaling results in insulin resistance with elevated insulin levels." (PMID 31788011, 2019). "Thus, the compromised neurotrophic action of insulin, due to defective insulin signaling, appears to be at the interphase between insulin resistance and PD pathogenesis." (PMID 31787891, 2019). "A recent meta-analysis of trials that evaluated the effect of omega-3 fatty acid supplementation on glucose control and insulin sensitivity among pregnant women with gestational diabetes mellitus found that supplementation resulted in reduced insulin resistance as measured by the HOMA-IR." (PMID 31783739, 2019). "As expected, fasting insulin levels were significantly higher in children who were overweight or obese compared to children of normal weight, potentially indicative of early signs of insulin resistance." (PMID 31623384, 2019). "Intracellular NEFAs inhibit insulin signaling, which will also lead to insulin resistance." (PMID 31569345, 2019). "Insulin resistance in endothelial cells can potentially play a role in glucose homeostasis through at least two mechanisms: The lack of a vasodilator effect of insulin and the reduction of the transendothelial delivery of insulin to its target tissues." (PMID 30754657, 2019). "However, both the QUICKI and HOMA methods have been validated for assessing insulin sensitivity and insulin resistance, respectively." (PMID 31805736, 2019). "We also calculated the index of insulin resistance and insulin sensitivity." (PMID 32010641, 2019). "In addition, HON treatment significantly decreased plasma insulin levels and improved impaired glucose tolerance and insulin resistance." (PMID 31075962, 2019). "Obesity and T2DM are closely related, since some altered obesity-induced conditions, such as excess of fat mass, systemic low-grade inflammation, altered insulin intracellular signaling and pancreatic β cells dysfunction, are involved in both insulin resistance and T2DM development." (PMID 31266190, 2019). "Thus, oxidative stress not only interferes with the insulin signal transduction pathway and promotes insulin resistance directly but can also hamper insulin signalling indirectly by inducing mitochondrial damage and mitophagy." (PMID 31130874, 2019).